FCGR3A (Fc gamma receptor IIIa)
Diseases named in the same sentence as FCGR3A in open-access papers (continued):
Sharing a sentence is not in itself a finding about the gene and the disease.
psoriasis (2 papers, 2024). An autoimmune condition characterized by red, well-delineated plaques with silvery scales that are usually on the extensor surfaces and scalp. "A previous study has discovered that the FCGR3A-V158F polymorphism was associated with the treatment of psoriasis patients." (PMID 39883516, 2024). "In current research, FCGR3A was identified as a potential target for psoriasis with robust evidence." (PMID 39883516, 2024). "Based on the GWAS data, further MR analysis and colocalization analysis genetically predicted that AIF1, FCGR3A, NEU1, HSPA1A, TNXB (Tenascin XB), and ABO were associated with psoriasis risk." (PMID 39883516, 2024). "Among these proteins, AIF1, FCGR3A (Fc gamma receptor IIIa), and NEU1 (neuraminidase 1) were considered the strongest candidates for psoriasis risk (PP.H4 = 1)." (PMID 39883516, 2024). "Moreover, FCGR3A was found to interact with known therapeutic targets of psoriasis such as CD2, Tumor necrosis factor (TNF), Integrin subunit alpha L (ITGAL), and IL17A." (PMID 39883516, 2024). "MR analyses unveiled 19 unique circulating proteins that were associated with psoriasis, among which only AIF1, FCGR3A, NEU1, HSPA1A, TNXB, and ABO were the potential proteins that interacted with psoriasis risk after being analyzed with high evidence of colocalization (PP.H4 > 0.9)." (PMID 39883516, 2024). "Furthermore, the study provided profound evidence for the role of FCGR3A in the pathogenesis of psoriasis." (PMID 39883516, 2024). "KO models on FCGR3A and ABO (alpha 1-3-N-acetylgalactosaminyltransferase and alpha 1-3-galactosyltransferase) showed phenotypes such as increased T-cell number, abnormal neutrophil physiology, and aberrant skin morphology suggesting a susceptible role in the pathogenesis of psoriasis." (PMID 39883516, 2024). "Combined with the protein target druggability, mouse KO models, and PPI network, FCGR3A, AIF1, and HSPA1A were highlighted for functioning as potential targets for psoriasis with strong evidence." (PMID 39883516, 2024). "By binding to IgG, FCGR3A participates in the induction and regulation of inflammatory processes, leading to the release of proinflammatory cytokines and other tissue-destructive mediators from activated monocytes/macrophages, which may contribute to the development of psoriasis." (PMID 39883516, 2024). "In addition, AIF1, FCGR3A, and HSPA1A have been finally determined to be feasible therapeutic targets for psoriasis after being confirmed by druggability verification and specific mouse knock-out models." (PMID 39883516, 2024). "In the meta-analysis, we found the minor allele of FCGR3A (rs396991) to be associated with poor response to TNFi and infliximab alone when pooling all CIDs together; similarly, this was observed for RA and IBD alone but not for psoriasis." (PMID 38891983, 2024).
schizophrenia (2 papers, 2021 to 2022). A major psychotic disorder characterized by abnormalities in the perception or expression of reality. "Exploration of FcGR3A and B cell activities would better determine the impact of IgG production and degradation in the schizophrenia midbrain." (PMID 35841099, 2022). "Gene transcript levels of FcGRT, FcGR3A, and FcGR2B were detected in the midbrain of both schizophrenia cases and control subjects." (PMID 35841099, 2022). "Low-inflammation schizophrenia cases and control subjects had comparable FcGR3A gene expression in the midbrain (p = 0.98)." (PMID 35841099, 2022). "In contrast, FcGRT and FcGR3A mRNA levels were elevated in the midbrain from “high inflammation” schizophrenia cases (FcGRT; p = 0.02, FcGR3A; p < 0.0001) in comparison to low-inflammation patients and healthy controls, while FcGR2B mRNA levels were unchanged." (PMID 35841099, 2022). "Although levels of IgG were unchanged between groups, a novel finding from this work is that people with schizophrenia have a robust increase in gene transcript levels of FcGR3A, a pro-inflammatory IgG receptor, in the midbrain." (PMID 35841099, 2022). "We found the high-inflammation biotype schizophrenia cases demonstrated increased expression of both the IgG transporter, FcGRT, and one of the pro-inflammatory receptors, FcGR3A." (PMID 35841099, 2022). "Based on a dichotomous variable indicating history of antidepressant use, schizophrenia cases that had been prescribed antidepressants had lower expression of FCGR3A and HEXB mRNAs." (PMID 34911938, 2021). "We speculate that IgG engaging with FcGR3A on phagocytic cells, such as microglia or macrophages, contributes to elevated cytokines in midbrain from high-inflammation biotype schizophrenia cases." (PMID 35841099, 2022). "Therefore, it is likely that elevated FcGR3A contributes to the pattern of increased levels of IL-1β, IL-6, and TNFα in the midbrain which can be used to define the high-inflammation biotype of schizophrenia." (PMID 35841099, 2022). "However, the same pattern of findings in the midbrain has also been found in the prefrontal cortex; levels of IgG in the brain were unaltered, and levels of FcGR3A were increased only in the high-inflammation schizophrenia subgroup in this region." (PMID 35841099, 2022). "This elevation in FcGR3A may also explain the increase in cytokine levels seen in the same midbrain region of high-inflammation schizophrenia patients." (PMID 35841099, 2022). "Interestingly, we found that the elevated levels of FcGR3A in the high-inflammation schizophrenia patients were negatively correlated with IgG levels in the midbrain." (PMID 35841099, 2022). "However, it is unknown whether the elevation of FcGR3A gene transcripts seen in the high-inflammation schizophrenia subgroup is related to this hyperdopaminergia." (PMID 35841099, 2022). "Similarly, FcGR3A mRNA in midbrain from high-inflammation biotype schizophrenia cases was increased by 275.1% when compared with control subjects (p < 0.001) and by 193.0% when compared with low-inflammation biotype schizophrenia cases (p < 0.001)." (PMID 35841099, 2022). "Therefore, increased dopaminergic activity in the midbrain of schizophrenia patients may stimulate an immune response in the brain, which might contribute to increased levels of FcGR3A." (PMID 35841099, 2022).
skin cutaneous melanoma (2 papers, 2022). "The “mutation” type of FCGR3A was the dominant type in skin cutaneous melanoma, with a frequency of approximately 3%." (PMID 35668930, 2022).
uveal melanoma (2 papers, 2022). A melanoma derived from melanocytes of the uveal tract. "In the GEPIA database, high FCGR3A expression was associated with poorer overall survival (OS) in LGG and uveal melanoma (UVM)." (PMID 39280892, 2022).
anaplastic thyroid carcinoma (1 paper, 2024). "A significant over expression of FCGR3A and LCP2 is found in anaplastic thyroid carcinoma (ATC)." (PMID 38568917, 2024).
appendicitis (1 paper, 2016). Acute inflammation of the vermiform appendix. "Interestingly, 3 of the 37 DEG (LILRA3, CXCR1/IL8RA, FCGR3A), which were higher in appendicitis patients compared to abdominal pain patients, are near or exact matches to transcripts discovered previously as down-regulated by exposure of isolated human neutrophils to E. Coli." (PMID 27417541, 2016).
autoimmune neurological diseases (1 paper, 2022). "The identified enhancer loop regulations in FCGR3A suggested potential therapeutic target in autoimmune neurological diseases." (PMID 35309301, 2022).
bipolar disorder (1 paper, 2021). A disorder of the brain that causes unusual shifts in mood, energy, activity levels and the ability to carry out day-to-day tasks. "In bipolar disorder cases that had been prescribed antidepressants, there was reduced expression of FCGR3A, IBA1 and P2RY12 mRNAs and higher expression of HEXB mRNA." (PMID 34911938, 2021).
bladder urothelial carcinoma (1 paper, 2022). "The mutation analysis found that the alteration frequency of FCGR3A in bladder urothelial carcinoma was the highest, and the main type is the amplification mutation." (PMID 35668930, 2022). "The alteration frequency of FCGR3A was the highest in bladder urothelial carcinoma (>15%), with “amplification” accounting for >90%." (PMID 35668930, 2022).
cardiomyopathy (1 paper, 2025). A disease of the heart muscle or myocardium proper. "Although IL1R1 has been implicated in aging-associated cardiomyopathy, FCGR3A, EphB3 and Serpin F1 have not been shown to have any effects." (PMID 41020515, 2025).
cervical cancer (1 paper, 2022). A primary or metastatic malignant neoplasm involving the cervix. "More interestingly, FCGR3A gene polymorphism was associated with an increased risk of low-grade precursor lesions of cervical carcinoma." (PMID 39280892, 2022).
Cirrhosis (1 paper, 2024). A chronic disorder of the liver in which liver tissue becomes scarred and is partially replaced by regenerative nodules and fibrotic tissue resulting in loss of liver function. "At the same time, the close relationship between the FCGR3A and FGL2 expression and immune cells might be a key factor in the development of cirrhosis of the liver." (PMID 39629005, 2024).
Cryptococcal meningitis (1 paper, 2012). Meningeal inflammation produced by cryptococcus neoformans, an encapsulated yeast that tends to infect individuals with acquired immunodeficiency syndrome and other immunocompromised states. "Distribution of FCGR2A, FCGR3A, FCGR3B, FCGR2B genotypes in patients with cryptococcal meningitis and controlsa." (PMID 22879986, 2012). "In this case control genetic association study, we genotyped four functional polymorphisms in low-affinity FcγRs, including FCGR2A 131H/R, FCGR3A 158F/V, FCGR3B NA1/NA2, and FCGR2B 232I/T, in 117 patients with cryptococcal meningitis and 190 healthy controls by multiplex SNaPshot technology." (PMID 22879986, 2012).
cryptococcosis (1 paper, 2012). An acute or chronic, localized or disseminated infection by Cryptococcus neoformans. "Meletiadis and colleagues genotyped FCGR2A 131H/R, FCGR3A 158F/V and FCGR3B NA1/NA2 in 103 cryptococcosis patients and 395 healthy controls." (PMID 22879986, 2012).
heart failure (1 paper, 2024). Inability of the heart to pump blood at an adequate rate to meet tissue metabolic requirements. "The expression of proteins involved in Ig-mediated immune activation [e.g., Fc Gamma Receptor IIIa FCGR3A], proteins associated with heart failure [e.g., Tenascin C (TNC), Quiescin sulfhydryl oxidase 1 (QSOX1)], was enhanced in severe MIS-C compared to KD." (PMID 39457139, 2024).
liver fibrosis (1 paper, 2025). "MF2 cells specifically expressed liver fibrosis-related genes AGTR1, CYGB, PIEZO2, and LPL, and MF5 cells specifically highly expressed immune-related genes TRAC, CD3D, GZMB, and FCGR3A." (PMID 40949143, 2025).
mastitis (1 paper, 2023). Inflammation of breast tissue during lactation or postpartum due to an obstructed duct or infection. "The FCGR3A (Fc fragment of IgG, low-affinity IIIa, receptor) gene is considered a novel and promising candidate for relieving stress, inflammation, and disease, as well as dairy-cattle mastitis." (PMID 37238084, 2023).
meningococcal infection (1 paper, 2020). Infections with bacteria of the species neisseria meningitidis. "FcγRIIa, FcγRIIIa, and FcγRIIIb, encoded by FCGR2A, FCGR3A, and FCGR3B, respectively, are shown to be important against meningococcal infection." (PMID 32067109, 2020).
mesothelioma (1 paper, 2022). A usually malignant and aggressive neoplasm of the mesothelium which is often associated with exposure to asbestos.
nasal polyps (1 paper, 2022). "Although not reaching statistical significance, the expression of FCGR3A did show an upward trend in nasal polyp tissues comparing with normal tissues (p = 0.093)." (PMID 36466903, 2022).
neuropathy (1 paper, 2022). A disorder affecting the nervous system that manifests with pain, tingling, numbness, and/or muscle weakness. "In addition, genetic markers such as FcγRIIIA polymorphisms in anti-MAG neuropathy and FCGR3A polymorphisms in NMO or generally studying the B cell receptor repertoire may prove to be of value." (PMID 35182380, 2022).
non-small cell lung carcinoma (1 paper, 2022). A group of at least three distinct histological types of lung cancer, including non-small cell squamous cell carcinoma, adenocarcinoma, and large cell carcinoma. "Long-term use of some common drugs leads to mutations in FCGR3A and related genes, which produces resistance to the disease, such as non-small cell lung cancer." (PMID 36505767, 2022).
renal carcinoma (1 paper, 2022). A carcinoma arising from the epithelium of the renal parenchyma or the renal pelvis. "The aim of the study was to assess the capabilities of mRNA genes encoding CD16a (FCGR3A) and CD16b (FCGR3B) proteins in tumor samples from patients with renal cancer, and characterize the tumor process in relation to clinical and morphological factors." (PMID 37064811, 2022). "The aim of the study was to assess the capabilities of mRNA genes encoding CD16a (FCGR3A) and CD16b (FCGR3B) in tumor samples from patients with renal cancer, and characterize the tumor process in relation to clinical and morphological factors." (PMID 37064811, 2022). "There is rather limited information on the interaction between the levels of mRNA genes encoding CD16a (FCGR3A) and CD16b (FCGR3B) in a tumor, and clinic and morphological factors determining a cancerous disease course including renal cancer." (PMID 37064811, 2022).
renal failure (1 paper, 2025). "The second is deletion and fusion of FCGR3A, with absence of ADCC, persistent EBV infection and renal failure." (PMID 40411624, 2025).
rheumatic disease (1 paper, 2017). "A novel association between the occurrence of LON and the possession of a SNP in the FCGR3A gene adds to the understanding of the LON phenomenon in patients with rheumatic disease treated with rituximab." (PMID 28270182, 2017).
spinal muscular atrophy (1 paper, 2019). A motor neuron disease that affect the muscles, and characterized by muscle weakness and atrophy resulting from progressive degeneration and irreversible loss of the anterior horn cells in the spinal cord (i.e., lower motor neurons) and the brain stem nuclei. "SMN gene deletion associated with spinal muscular atrophy (SMA) was not reported in PPS, but Fc-gamma receptor IIIA polymorphisms may play a role in the predisposition to PPS." (PMID 31379723, 2019).
substance dependence (1 paper, 2025). The psychological or physiological need to take a substance in order to experience its effects or to avoid the effects of its absence. "Drugs aimed at ERBB2, FCGR3A, and FLT3 are primarily used in treating various cancers and benign tumors, while ALDH2 is targeted in therapies for a range of systemic diseases, notably cancer and substance dependence." (PMID 40868097, 2025).
uveitis (1 paper, 2018). An inflammatory process affecting a part of or the entire uvea. "A Korean study tested a number of gene variants including FCGR3A in a cohort of 61 BD patients with severe uveitis and also found a significant association (p = 0.047) with FCGR3A/rs39699127." (PMID 29555961, 2018).
vitiligo (1 paper, 2025). Generalized well circumscribed patches of leukoderma that are generally distributed over symmetric body locations and is due to autoimmune destruction of melanocytes. "In the smoking population, the number of FCGR3A+ Cytotoxic CD8 + T cell subset was significantly elevated, suggesting immune activation and implying a potential association between smoking and the development of vitiligo." (PMID 41438750, 2025). "Our analysis revealed dynamic alterations and functional roles of KLRC2+ NK cells, Treg cells, FCGR3A+ Cytotoxic CD8 + T cells, and EGR1+ B cells, opening new avenues for systemic immunology-oriented research in vitiligo." (PMID 41438750, 2025).
tumor (238 papers, 2007 to 2026). "The analysis showed that FCGR3A expression was associated with tumor purity in 28 cancer types and B cell infiltration levels in 24 cancer types." (PMID 39280892, 2022). "This suggested that FCGR3A is extensively implicated in the negative regulation of tumor angiogenesis and the regulation of cancer immune signaling pathways." (PMID 35668930, 2022). "C1Q Macros expressed C1QA/B/C genes similarly to MAFB+ LC, but uniquely expressed FCGR3A and were enriched in a C1Q tumor-associated macrophage (TAM) gene-set." (PMID 36741389, 2022). "In the present study, we report a significant influence of FCGR3A F158V polymorphism on survival both in the whole population and in patients with a wt KRas tumor, with VV patients presenting a dramatically shorter survival." (PMID 22117530, 2011). "Moreover, CAR-modified NK-92 cell lines against various tumor types and an NK-92 cell line expressing the high-affinity 176V variant of FCGR3A, also called high-affinity NK (haNK), have been reported." (PMID 39051331, 2024). "Interestingly, FCGR3A expression was significantly associated with gene markers of B cells, monocytes, tumor-associated macrophages (TAMs), M2 macrophages, DCs, Th2 cells, and T cell exhaustion in LGG." (PMID 39280892, 2022). "Third, although we identified that FCGR3A expression was associated with survival in some tumor patients and affected immune cell infiltration, we were unable to prove a clear causal relationship between FCGR3A altering immune infiltration and affecting patient survival." (PMID 35668930, 2022). "The emergence of such mutations exclusively in patients expressing the FCGR3A V allele indicates that avelumab’s therapeutic pressure may largely be mediated by tumor-infiltrating innate immune effector cells, especially NK cells." (PMID 35936668, 2022). "FCGR3A was proved to be associated with anti-tumor response." (PMID 31956364, 2020). "Our analysis revealed that FCGR3A and FGL2 expression was significantly correlated with clinical variables such as age, tumor type, WHO grade, histology, IDH-1 mutation, and 1p19q status." (PMID 39629005, 2024). "FCGR3A/FCGR3B emerged as a potentially druggable gene, predominates as a risk prognostic factor in most cancers, and is closely related to tumor immune-related pathways." (PMID 38339034, 2024). "In vitro experiments and tissue immunofluorescence staining revealed that FCGR3A can promote the infiltration or polarization of M2 macrophages and enhance tumor proliferation and migration." (PMID 39574475, 2024). "The relevance of FCGR3A in PDAC complements existing evidence on the role of the tumor microenvironment in cancer progression." (PMID 39574475, 2024). "Genes such as ADGRG1, TBX21, S1PR5, FCRL6, and FCGR3A showed relatively selective expression in tumor-reactive T cells (the average expression in bystander T cells < 0.5)." (PMID 39243082, 2024). "The MARCO, CD14, FCGR3A, and CD163 genes, which are unique to tumor-associated macrophages (TAMs), were expressed in cluster two." (PMID 38096229, 2023). "IGKC, SCGB1A1 HSPB1, and FCGR3A were found to be differentially expressed in normal tissue compared with tumor and metastasis." (PMID 37335089, 2023). "This study aimed to visualize the prognostic landscape of FCGR3A in pan-cancer and investigate the relationship between FCGR3A expression and tumor microenvironment." (PMID 35668930, 2022). "More importantly, FCGR3A expression positively correlated with immune checkpoint molecules, including PD1, PD-L1, PD-L2, CTLA4, LAG-3 and TIM-3, and tumor-associated macrophage (TAM) gene markers in LGG." (PMID 39280892, 2022). "We were surprised to find that FCGR3A expression was inconsistent with clinicopathological features in age and GS, while consistent with clinicopathological features in tumor stage (TMA, P=0.030; TCGA, P=0.006)." (PMID 36505767, 2022).